RN7SL568P (RNA, 7SL, cytoplasmic 568, pseudogene)
Gene: Miscellaneous RNA gene on chromosome 15 (56,029,684 to 56,029,981, reverse strand). Ensembl gene ENSG00000239703.
Homologues: Orthologues: chimpanzee Metazoa_SRP (95% identical), macaque Metazoa_SRP (88% identical). Paralogues in human: RN7SL2 (80% identical), RN7SL1 (79% identical), RN7SL45P (78% identical), RN7SL3 (78% identical), RN7SL326P (77% identical), RN7SL615P (76% identical), RN7SL126P (76% identical), RN7SL186P (76% identical), RN7SL660P (76% identical), RN7SL386P (76% identical), RN7SL478P (76% identical), RN7SL556P (76% identical), and 700 more.